BMP2 (bone morphogenetic protein 2)
Diseases named in the same sentence as BMP2 in open-access papers (continued):
Sharing a sentence is not in itself a finding about the gene and the disease.
glioma (36 papers, 2008 to 2025). A benign or malignant brain and spinal cord tumor that arises from glial cells (astrocytes, oligodendrocytes, ependymal cells). "Our study also showed that BMP2 overexpression was significantly associated with better survival and delayed disease progression in patients with glioma." (PMID 38672212, 2024). "The results showed that nine genes were associated with the survival time of patients, among which BMP2 and AR were protective factors in glioma patients, and the other seven genes were risk factors." (PMID 39458959, 2024). "In this study, five prognosis-related differentially expressed immune-related genes (PR-DE-IRGs) (CCNA2, HMGB2, CASP3, APOBEC3C, and BMP2) highly associated with glioma were identified for a prognostic model through weighted gene co-expression network analysis, univariate Cox and lasso regression." (PMID 35601497, 2022). "In different grades of gliomas, the expression of BMP2 mRNA in IDH1-mutated gliomas was higher than that in wild-type gliomas (t = 15.374, p = 0.000), and the expression of BMP2 mRNA in 1p19q loss of heterozygosity status was higher than that in the intact (t = 16.329, p = 0.000)." (PMID 33116227, 2020). "Furthermore, our RNA‐sequencing data demonstrated that 3 of the genes (SCN5A, L1CAM, BMP2) affected with the anti‐ELTD1 treatment that were directly associated with gliomas influenced and interacted with Notch signalling." (PMID 31863639, 2020). "Therefore, we believe that similarly to FSTL1, CER1 may also inhibit the activation of the BMP2 pathway, which would induce undifferentiation of glioma cells and cause poor prognosis in patients with glioma." (PMID 38672212, 2024). "In glioma, cell death-related risk signatures (FANCD2, RRM2, BMP2, NFE2F2, MYD88) have been identified and validated using machine learning." (PMID 40559911, 2025). "When the patients were again divided based on the WHO grade, BMP2 showed significantly lower expression in grade III gliomas than in grade II gliomas." (PMID 38672212, 2024). "The effects of BMP2 and AR on glioma reported in the literature are consistent with the results of this study showing that BMP2 and AR are protective factors in glioma patients." (PMID 39458959, 2024). "Functional modeling on pediatric glioma cell lines and spatial transcriptomics unveil that H3.3K27M and BMP2/7 synergize to induce a transcriptomic switch leading to a quiescent but invasive cell state." (PMID 39373720, 2024). "Although BMP2 was significantly associated with both OS and PFS in grade II and III gliomas, a more significant difference was observed in grade III gliomas than in grade II gliomas." (PMID 38672212, 2024). "The BMP2/7-driven cell state that we described here fits with previous results obtained in other glioma models, in which a subpopulation of quiescent cells was identified as partially responsible for tumor invasiveness, a hallmark of pDMG aggressiveness." (PMID 39373720, 2024). "Of these additional genes, the higher expression of four genes (BMP2, RPL18A, RPL19, and RPS12) was also significantly associated with better survival and delayed tumor recurrence in patients with glioma, especially those with grade III glioma." (PMID 38672212, 2024). "The findings validate that HADHA and BMP2 exhibit significant expression levels in glioma tissues, potentially playing a role in the development and advancement of glioma." (PMID 38566075, 2024). "The higher expression of BMP2, RPL18A, RPL19, and RPS12 is associated with better outcomes in patients with glioma." (PMID 38672212, 2024). "The transient receptor potential melastatin family member 8 (TRPM8), bone morphogenetic protein 2 (BMP2) and L1CAM are upregulated in GBMs compared to normal brain tissue and are associated with glioma cell proliferation, migration and invasion." (PMID 34910361, 2022).
glioma (continued). "We also constructed a comprehensive competing endogenous RNA (ceRNA) regulatory network based on the protective factor BMP2 to further explore its potential role in glioma progression." (PMID 35601497, 2022). "Consistent with our previous findings, the expressions of NUP107, DRAM1, RNF19A, PXDN, HEY2, F2R, and BMP2 were up-regulated in gliomas (glioblastoma multiforme + lower grade glioma)." (PMID 36245971, 2022). "BMP2 and HEY2 were identified as protective factors (HR < 1), and NUP107, DRAM1, F2R, PXDN, RNF19A, and SCG5 were identified as risk factors for glioma (HR > 1)." (PMID 36245971, 2022). "BMP2 increased the differentiation and apoptosis of glioma in a concentration-dependent manner through the downregulation of both MGMT and hypoxia-inducible factor-1 (HIF-1) (xref>/xref>)." (PMID 35982954, 2022). "In gliomas, BMP2 and BMP4 have been proposed to be a potential predictor for the prognosis of patients." (PMID 34357080, 2021). "Last, mining of the diffuse low-grade glioma subset of the TCGA database shows that expression of BMP2/4 is highly correlated to the expression of the BMP-inhibitor NOG (NOGGIN) gene." (PMID 33925547, 2021). "We confirmed this tight correlation by performing QPCR for NOG in the five diffuse low-grade glioma resections we previously analyzed for BMP2/4." (PMID 33925547, 2021). "BMPs, e.g., BMP2/4/7, and their downstream signaling, type I receptor, have been found for their potential inhibitory roles in glioma tumorigenicity since 2006." (PMID 34357080, 2021). "This study aimed to establish a new glioma grading model by analyzing the expression of Bone Morphogenetic Protein 2 (BMP2) mRNA in patients with gliomas as well, named the Histopathological-BMP2 (HB) system." (PMID 33116227, 2020). "In the company of low BMPR1B expression, BMP2 increased the differentiation and apoptosis of glioma in a concentration dependent manner." (PMID 33116227, 2020). "A new glioma grade (HB grade) based on histopathology and BMP2 expression can predict the prognosis of glioma patients, with BMPR1B and BMPR2 expression indicating a different prognosis in different types of gliomas." (PMID 33116227, 2020). "We established a new glioma classification model based on histochemistry and BMP2 expression (HB classification: HBs: rO, rAO, rOA; HBh: O, AO, OA; HBm: AOA, rAOA, A, rA, AA, rAA; HBl: GBM, rGBM), which is related to the prognosis of patients." (PMID 33116227, 2020). "ADA and BMP2 expression are correlated with poor prognosis in glioma patients, which were both down‐regulated with the anti‐ETLD1 treatments." (PMID 31863639, 2020). "The effect of BMP2 on glioma differentiation and apoptosis is receptor dependent, which mainly depends on the receptor BMPR1B." (PMID 33116227, 2020). "At the same time, we used this classification model to explore the mechanism of interaction between BMP2 and its receptors in different grades of gliomas." (PMID 33116227, 2020). "The role of BMP2 in promoting tumor differentiation and apoptosis in different types of gliomas is mainly attributed to its BMPR1B receptor dependence and its own concentration dependence." (PMID 33116227, 2020). "In this study, we reclassified glioma patients based on both histopathological characteristics and BMP2 messenger RNA (mRNA) expression and verified the predictive value of survival and prognosis of this classification model." (PMID 33116227, 2020). "Patients with gliomas were classified into four grades on the basis of both histopathological characteristics and the expression of BMP2 mRNA." (PMID 33116227, 2020). "In 2009, Liu and coworkers reported that BMP2 expression became significantly higher as the glioma's grade advanced (P < 0.001) and the Karnofsky Performance Status (KPS) score decreased." (PMID 24877113, 2014).
glioma (continued). "With respect to potential consequences of these gene expression changes, BMP-2 has been shown to induce differentiation of glioma stem-like cells and, thus, modulate chemosensitivity in vitro." (PMID 25464980, 2014). "Additional studies employing larger microarray databases available nowadays should confirm the view that the role of BMP4 and BMP7 in glioma differs from that of BMP2." (PMID 24877113, 2014). "Also, BMP2 has been widely reported on, such as in correlation to poor prognosis in glioma patients and part of a proposed glioma grading model." (PMID 39941811, 2025). "In addition, the overexpression of CER1, a BMP antagonist, inhibits BMP2 to induce undifferentiated glioma cells." (PMID 38672212, 2024). "Moreover, FXYD6 was pertinent to the several classic EMT genes in gliomas (BMP2, TAB1, and so on) (|r| > 0.35, p < 0.05)." (PMID 38093622, 2023). "This suggests that BMP2 increased after glioma recurrence with oligodendrites." (PMID 33116227, 2020). "BMP2 increased the differentiation and apoptosis of glioma in a concentration dependent manner." (PMID 33116227, 2020). "BMP2 is typically expressed by glioma with a 1p19q codeletion." (PMID 23805239, 2013). "This confirmed that gliomas with 1p19q codeletion overexpressed neuronal/normal brain genes (AKR1C3, C20orf42, CTTNBP2, L1CAM, GALNT13) as well as genes implicated in gliogenesis and neurogenesis (OLIG2, BMP2, NOG, DCX, ATOH8)." (PMID 18492260, 2008). "While BMP2 promotes differentiation in glioma stem-like cells under specific conditions, its upregulation in bulk tumor tissue—as observed here—may instead reflect a non-functional or dysregulated compensatory response, possibly driven by an immunosuppressive or mesenchymal microenvironment." (PMID 40869118, 2025). "A genome-wide association study suggested that increased European ancestry in non-European population might be associated with the occurrence of glioma and identified four novel susceptibility variants, including 7q21.11 (SEMA3A), 11p11.12 (Intergenic), 12q24.21 (RBM19) and 20p12.13 (HAO1, BMP2)." (PMID 33430813, 2021). "Conversely, the expression of genes related to good prognosis, such as FRAT1 and BMP2, was significantly lower in grade III than in grade II gliomas." (PMID 38672212, 2024). "But we still failed to verify the significant differential relative mRNA expression of BMP2 and NUP107 between gliomas and adjacent normal tissues." (PMID 36245971, 2022). "The expression level of BMP2 is related to the degree of tumor malignancy and GBM patient survival; therefore, it is being considered as a prognostic marker for glioma." (PMID 35982954, 2022). "LncRNA PVT1 promotes the expression of BMP2 and BMP4 by regulating GREM1 expression and promoting glioma progression." (PMID 35113786, 2022). "A potential link between CRYAB, NOTCH1, and BMP pathways is also supported by diffuse low-grade glioma RNA profiles in the TCGA database, showing a significant correlation between CRYAB, BMP2, and HEY2 expression." (PMID 33925547, 2021). "It is suggested that BMP2 and BMPRIB are the key factors to promote the apoptosis and differentiation of tumors and lead to different types of gliomas with different prognosis." (PMID 33116227, 2020). "According to pathological glioma subtypes and the expression of BMP2 mRNA in tumor tissues, the new subtypes HBs, HBh, HBm and HB1 were established, with BMP2 expression highest in HBs and lowest in HB1." (PMID 33116227, 2020). "The expression of BMP2 and BMPR1B are different in different types of gliomas, and their different combinations lead to different prognosis of different types of gliomas." (PMID 33116227, 2020). "Furthermore, BMP2, NCF1, HSPB1, PIGT, PTX3, CCNA2, and CCNB2 exhibited increased expression, while DES displayed decreased expression in glioma tissues." (PMID 40656950, 2025). "Based on our findings, we hypothesized that the effects of FSTL1 and CER1 in grade III gliomas are stronger, whereas those of FRAT1 and BMP2 are weaker." (PMID 38672212, 2024).
glioma (continued). "In contrast, if the actions of FRAT1 and BMP2 become stronger and those of FSTL1 and CER1 become weaker in patients with grade III gliomas, the difference in survival and disease progression between these opposing groups may significantly increase." (PMID 38672212, 2024). "Still only BMP2, MMP13, MMP2, LCK, MMP9, and AR have been reported to affect the glioma invasion." (PMID 39458959, 2024). "By using both pediatric isogenic glioma lines genetically modified to overexpress H3.3K27M and patients-derived DIPG cell lines, we demonstrate that BMP2/7 synergizes with H3.3K27M to induce a transcriptomic rewiring associated with a quiescent but invasive cell state." (PMID 39373720, 2024). "ADAM17 and MAML3 are indexed in the KEGG “Notch signaling pathway”, and BMP2 and SMAD5 are indexed in the KEGG “TGF-beta signaling pathway”, which confirms our data on the involvement of these processes in the formation of glioma neurospheres." (PMID 36231068, 2022). "The cross-union protocol did work without BMP2 in one case in this study in which BMP2 was contraindicated due to a glioma." (PMID 34202921, 2021). "BMP2 did not increase after the recurrence of gliomas containing astrocytes or GBM." (PMID 33116227, 2020). "However, the expression levels of BMP2 and GDF10 were significantly positively correlated with the overall survival in glioma patients, which is inconsistent with the previous findings, suggesting that TGF-β family genes have complex regulatory functions in gliomas." (PMID 37867596, 2023).
lung carcinoma (35 papers, 2010 to 2024). "BMP2-induced lung cancer migration is associated with up-regulation of Runx2 which recruits p300 and in turn enhances histone acetylation, increases Snail expression, and decreases E-cadherin." (PMID 25938545, 2015). "BMP2 knockdown caused a significant increase in the percentage of dead lung cancer cells growing in SFM." (PMID 23593444, 2013). "Mouse models for lung cancer associate elevated BMP2 levels with increased malignancy, promoted lung tumor growth and stimulated angiogenesis in developing tumors." (PMID 23560048, 2013). "A recent report shows that the migration of lung cancer cells is associated with the upregulation of Runx2 and Snail expression in response to BMP-2 treatment." (PMID 22537242, 2012). "To further test the role of BMP2 in lung cancer metastasis, we treated CL1-0, CL1-5, PC14PE6, and AS2 cells with rhBMP2 to activate the BMP signaling pathway." (PMID 36175474, 2022). "BMP2:rs235756 has previously been reported as a significant biomarker for OS in patients with lung cancer." (PMID 34307117, 2021). "At present, approximately 20 BMPs have been identified; however, most studies involving BMPs in lung cancer have focused on BMP2, BMP4, and BMP7." (PMID 34745928, 2021). "BMP2 is highly expressed in lung cancer and is involved in regulating lung cancer angiogenesis and metastasis." (PMID 34307117, 2021). "BMP2 silencing inhibited the proliferation and migration of lung cancer cells, and BMP2 signaling activation promoted bone metastases and invasion in NSCLC." (PMID 34036102, 2021). "As a close relative of BMP2, the upregulation of BMP4 has been proven to be strongly associated with EGFR-TKI resistance and fatty acid metabolism in lung cancer." (PMID 34745928, 2021). "Among BMPs, overexpression of BMP2 was indicated to occur in ~98% of lung carcinomas and to contribute to lung cancer progression." (PMID 33123465, 2020). "BMP2 signalling regulates the interaction among lung cancer cells, osteoblasts and macrophages to promote the osteoclasts differentiation, further enhancing osteolysis in bone metastases." (PMID 32750747, 2020). "We find that BMP2 signalling can promote bone metastases of lung carcinoma from multiple directions." (PMID 32750747, 2020). "BMP-2 knockdown in lung cancer cell lines A549 and H460 suppressed their proliferation and migration." (PMID 27886213, 2016). "Lung cancer patient data analysis indicated strong correlation between LKB1 loss-of-function mutations and high BMP2 expression, and these two events further correlated with expression of a gene subset functionally linked to apoptosis and migration." (PMID 26701726, 2016). "In the lung cancer model, inhibited BMP2 activity resulted in reduced tumor growth, whereas in this model of metastatic esophageal cancer, increased BMP2 activity reduced tumor growth." (PMID 27230238, 2016). "This hints to a prognostic relevance of the BMP2 effect in lung cancer, which is independent from stage and tumor burden." (PMID 25924783, 2015). "BMP2 serum levels have been shown to be higher in lung cancer patients than in normal healthy controls." (PMID 25924783, 2015). "In this study, we used siRNA to silence BMP-2 to observe the effect on proliferation and migration of the lung cancer cell lines A549 and H460." (PMID 24946687, 2014). "We have demonstrated that lung cancer cells can not only secrete IL-8 to promote osteoclastogenesis but also trigger osteoblast to secrete bone morphogenetic protein-2 (BMP-2), which in turn promotes lung cancer migration, invasion, and EMT." (PMID 25937967, 2014). "This outcome is in accordance with previous studies and further confirms the biological function of BMP-2 in lung cancer." (PMID 24946687, 2014).